CDK4 (cyclin dependent kinase 4)
Diseases named in the same sentence as CDK4 in open-access papers (continued):
Sharing a sentence is not in itself a finding about the gene and the disease.
thyroid tumor (4 papers, 2013 to 2023). A benign or malignant neoplasm affecting the thyroid gland. "Nevertheless, high CDKN2A mRNA levels were also found in some profiles H and L thyroid tumors (associated with CDK4 phosphorylation)." (PMID 37964967, 2023). "We tested thyroid tumor cell lines for susceptibility to palbociclib (PD-0332991), a specific inhibitor of Cyclin D1 associated kinases CDK4/6." (PMID 26431489, 2015). "Such a binary classification of thyroid tumors, which distinguishes tumors with intrinsic resistance to CDK4/6i from tumors expressing the drug target, would meet the clinical need." (PMID 37964967, 2023). "To conclude, our study supports the potentially favorable clinical impact of CDK4/6i for the treatment of aggressive dedifferentiated thyroid tumors including in combinations with anti-BRAF/MEK and, likely, anti-ERK therapies." (PMID 37964967, 2023). "Overall, these observations support the potentially favorable clinical impact of inhibiting CDK4 activation in some thyroid tumors." (PMID 37964967, 2023). "The accuracy (proportion of predictions matching the observations) reached only 57.4% when applied to the prediction of the three CDK4 modification profile in thyroid tumors." (PMID 37964967, 2023). "Molecular analyses in these mice revealed the activation of the cyclin 1–cyclin-dependent kinase-4–transcription factor E2F1 pathway, known to be associated with thyroid tumour cell proliferation." (PMID 24683474, 2013). "Moreover, MAPK/ERK, EGFR/ERBB and PI3K/AKT, widely recognized as the main deregulated signaling pathways in thyroid tumors, have CDK4/6 as major integrating node." (PMID 37964967, 2023). "Our study supports further clinical evaluation of CDK4/6i and their combination with anti-BRAF/MEK therapies as a novel effective treatment against advanced thyroid tumors." (PMID 37964967, 2023).
urothelial carcinoma (4 papers, 2017 to 2022). A malignant neoplasm derived from the transitional epithelium of the urinary tract (urinary bladder, ureter, urethra, or renal pelvis). "IHC staining for CDK6 protein in urothelial carcinoma is proposed as a promising screening platform for CDK4/6 inhibitor targeted therapy." (PMID 35463324, 2022). "Furthermore, we found that urothelial carcinoma cell lines with higher CDK6 expression levels displayed greater sensitivity to CDK4/6 inhibitors than cells with lower expression levels." (PMID 35463324, 2022). "Furthermore, studies have shown that CDK6 expression is elevated in urothelial carcinoma tissue compared to the surrounding urothelium, thus presenting a case for performing CDK4/6 inhibitor targeted research in urothelial carcinoma." (PMID 35463324, 2022). "Urothelial carcinomas with papillary patterns showed lower parameters of CDK4 and STAT3 expression compared to the non-papillary variant, with significant differences." (PMID 32102537, 2020). "Urothelial carcinomas with papillary patterns showed lower parameters of CDK4 expression compared to the non-papillary variant, with significant differences for CDK4 percent (p<0.01) and score (p<0.01)." (PMID 32102537, 2020). "We selected two urothelial carcinoma cell lines, T24 and 5637, with different CDK6 protein expression levels, to observe the inhibitory effect of CDK4/6 inhibitors." (PMID 35463324, 2022). "We show here that the combination therapy of the CDK4/6 inhibitor Palbociclib and the PARP inhibitor Talazoparib has synergistic anticancer effects on RB-positive urothelial carcinoma cells in vitro and in xenograft models." (PMID 33923231, 2021). "miR-34a negatively regulates the cell cycle by reducing CCND1 (cyclin D1) and CDK4 (cyclin dependent kinase 4) levels; its downregulation promotes a more aggressive behavior of FGFR3 in urothelial carcinoma cases." (PMID 29165379, 2017). "In this study, we observed the activity of CDK6 in urothelial carcinoma cases and defined about 28% (24/85) CDK6 high expression cases with unknown CDK4 state." (PMID 35463324, 2022). "However, a phase II trial showed that CDK4/6 inhibitors are not effective for advanced urothelial carcinoma, suggesting that case screening is important for targeted therapy." (PMID 35463324, 2022).
venous thromboembolism (4 papers, 2024 to 2025). Occlusion of the lumen of a vein by a thrombus that has migrated from a distal site via the blood stream. "Among all trial participants, the addition of CDK4/6i significantly increases the risk of venous thromboembolism (RR = 2.65; 95% CI: 1.40–5.00; p = 0.03)." (PMID 40922517, 2025). "Clinicians need to be aware of hematological toxicities, abnormal liver function, and venous thromboembolism in the use of CDK4/6 inhibitors." (PMID 40922517, 2025). "Clinicians should be aware of hematological toxicities, liver function abnormalities, and venous thromboembolism when using CDK4/6 inhibitors." (PMID 40922517, 2025).
viral infection (4 papers, 2017 to 2022). "Although viral infection also resulted in cyclin D1, CDK4, and CDK6 down-regulation on protein level, the level of down-regulation is not as robust as that of cyclin D3, and their protein levels could not be rescued by protease and calpain inhibitor when compared with cyclin D3." (PMID 28130444, 2017).
xeroderma pigmentosum (4 papers, 2020 to 2024). Xeroderma pigmentosum (XP) is a rare genodermatosis characterized by extreme sensitivity to ultraviolet (UV)-induced changes in the skin and eyes, and multiple skin cancers. "For instance, heritable mutations such as in MC1R, CDK4, and CDKN2A, as well as genetic conditions like xeroderma pigmentosum (XP), have all been associated with an increased risk of melanoma development." (PMID 38067178, 2023).
adenosarcoma (3 papers, 2017 to 2023). A low grade malignant neoplasm characterized by the presence of a benign epithelial component (tubular and cleft-like glands) and a low grade sarcomatous component that contains varying amounts of fibrous and smooth muscle tissues. "A recent large next-generation sequencing study of atypical uterine polyps (polyps with atypical stromal features exhibiting some morphologic overlap with adenosarcomas) also confirmed focal gene amplifications of CDK4 and MDM2, among other loci." (PMID 35798968, 2022). "Conversely, MDM2/CDK4 amplifications, a consistent finding in approximately a quarter of adenosarcomas, were absent in PTs." (PMID 28267263, 2017). "Focal amplifications in 12q14.1‐15, encompassing the loci of MDM2 and CDK4, were significantly more prevalent in adenosarcomas than in PTs (26% vs 0, Fisher's exact test, P = 0.0155)." (PMID 28267263, 2017). "PTs significantly more frequently displayed mutations affecting MED12, the TERT gene promoter and bona fide cancer genes, whereas adenosarcomas harbored a higher rate of MDM2/CDK4 and TERT gene amplifications." (PMID 28267263, 2017). "Amplifications of MDM2/CDK4 remained significantly more prevalent in low‐grade adenosarcomas than in all PTs (Fisher's exact test, P = 0.0242)." (PMID 28267263, 2017). "Meanwhile, MDM2, CDK4, HMGA2, and GLI1 gene amplifications are common molecular events in Müllerian adenosarcoma, often seen in patients with SO." (PMID 37810911, 2023). "We did not identify CDK4 or MDM2 gene amplifications, pointing to significant differences between EMPs and atypical uterine polyps/adenosarcomas." (PMID 35798968, 2022).
adenovirus infection (3 papers, 2016 to 2022). "The results clearly showed that the expression of CDK6, not CDK4, inhibited by matrine was significantly rescued by the c-Myc adenovirus infection, not by the Control adenovirus infection, in SU-DHL-16 cells, which identified that CDK6 is a bona fide c-Myc target gene in SU-DHL-16 cells." (PMID 34088288, 2021).
anaplastic astrocytoma (3 papers, 2019 to 2021). "Previous studies have shown that the expression of CDK4 at the mRNA level was significantly increased in anaplastic astrocytoma and glioblastoma tumors when compared to adjacent normal brain tissues." (PMID 33321738, 2020).
Arthralgia (3 papers, 2021 to 2023). "Arthralgia has been more frequently reported in patients treated with palbociclib compared with the other two approved CDK4/6 inhibitors." (PMID 34198899, 2021). "Arthralgia was reported in 1–47% of patients treated with AIs and 5.8–33.3% of patients treated with CDK4/6 inhibitors." (PMID 33530456, 2021). "Considering this deviation from the expected incidence of arthralgia, we evaluated arthralgia incidence in patients treated with CDK4/6 inhibitors in our institution." (PMID 34198899, 2021).
bladder urothelial carcinoma (3 papers, 2018 to 2021). "In this study, we approached this by developing an OH-BBN induced urothelial bladder cancer model that combines two pro-oncogenic factors, overexpression on Hgf and an activating mutation in Cdk4 (R24C)." (PMID 34232958, 2021). "Correspondingly, proteins related to cell cycle such as CDK4, CDK6 and Cyclin D1 were obviously diminished after specific siRNA treatment, which is consistent with the phenomenon that bladder urothelial carcinoma cells are largely arrested in the G1 phase." (PMID 33980246, 2021). "According to the Pathology Atlas of the Human Cancer Transcriptome high mRNA expression of HGF or CDK4 in urothelial bladder cancer correlates with a worse overall survival compared to patients with low expression of these genes (P-scores: HGF 0.021 and CDK4 0.016)." (PMID 34232958, 2021).
bone sarcoma (3 papers, 2023 to 2024). A sarcoma that arises from the bone. "The immunohistochemical analysis of MDM2, CDK4, and SATB2 in this case report was positive, indicating that this spindle cell sarcoma belongs to the category of bone sarcomas." (PMID 39634267, 2024).
Cerebral ischemia (3 papers, 2021 to 2022). Restriction of arterial blood supply to the brain associated with insufficient oxygenation to support the metabolic requirements of the tissue. "Significant disproportionalities emerged also for transient ischemic attacks, cerebral ischemia, paraplegia, and paraparesis, with a more rapid time to onset than other CDK4/6 inhibitors (1 vs. 6 months, respectively)." (PMID 33917020, 2021). "In animal models of brain and spinal cord ischemia, cyclin D1 and cdk4 expressions are increased in neurons and/or glial cells after focal brain ischemia in mice and rats, global brain ischemia in rats, and spinal cord ischemia in rabbits." (PMID 34439951, 2021). "Inadequate activation of cell cycle proteins including cyclin D1 and cdk4 is involved in neuronal cell death induced by diverse pathological stresses, including transient global brain ischemia." (PMID 34439951, 2021).
Childhood Cancer (3 papers, 2013 to 2023). "g. using inhibitors to FGFRs, Aurora A kinase and CDK4, which might lead the way to an effective clinical therapy for this lethal pediatric cancer." (PMID 24204904, 2013).
chronic hepatitis (3 papers, 2009 to 2020). An active inflammatory process affecting the liver for more than six months. "Previously, protein levels and kinase activities of cyclin D1, E, Cdk4, cyclin A, and Wee1 were demonstrated to increase proportionally with the development of HCC, especially in the transition process from chronic hepatitis to HCC." (PMID 22539975, 2012). "In another in vitro study protein levels and activities of cyclin D1, E, Cdk4, cyclin A and Wee1 increased proportionally with the development of HCC, especially in the transition process from chronic hepatitis to HCC." (PMID 27942274, 2009).
chronic kidney disease (3 papers, 2022 to 2024). Impairment of the renal function secondary to chronic kidney damage persisting for three or more months. "Blocking CDK4/6 improved renal function and reduced tubular injury and fibrosis in 2 murine models of chronic kidney disease." (PMID 35730565, 2022). "In conclusion, blocking cell cycle progression by inhibiting CDK4 may protect against chronic kidney disease by preventing damaged proximal tubule cells from proliferating by reducing tubular injury, fibrosis and senescence." (PMID 36979798, 2023). "Two weeks after initiation of chronic kidney disease, we blocked cell cycle progression at G1/S phase by using an FDA-approved, selective inhibitor of CDK4/6." (PMID 35730565, 2022). "At the time of CDK4/6 inhibitor initiation, sCr was 1.25 mg/dL (normal range value 0.6-1.3mg/dL), corresponding to a 45 mL/min/1.73 m2 eGFR calculated by the 2021 CKD-EPI creatinine equation, without evidence of proteinuria (stage G3bA1 chronic kidney disease (CKD))." (PMID 39318897, 2024).
endometrial stromal sarcomas (3 papers, 2022 to 2025). "Molecular biologically, endometrial stromal sarcomas with BCOR rearrangement bear common MDM2 amplification and activation of the cyclin D1-CDK4 pathway by CDK4 amplification by cyclin D1 protein overexpression or CDKN2A deletion." (PMID 35242139, 2022).
Insulin resistance (3 papers, 2023 to 2025). Increased resistance towards insulin, that is, diminished effectiveness of insulin in reducing blood glucose levels. "BrdU incorporation was only significantly increased by Cdk4-R24C in the Irs2–/– context, suggesting the proliferation was amplified by insulin resistance." (PMID 37712417, 2023). "Cyclin D2 drives β cell compensation in response to insulin resistance, but islet cyclin D2 levels are reduced in Irs2–/– mice; rescue by Cdk4-R24C makes sense in this context." (PMID 37712417, 2023). "Insulin resistance in Irs2–/–;Cdk4-R24C/R24C mice likely contributed to increased proliferation." (PMID 37712417, 2023). "Finally, given the hyperinsulinemia in response to insulin resistance in Irs2–/–;Cdk4-R24C/R24C, CDK4 may synergize with activation of the unfolded protein response to drive β cell proliferation." (PMID 37712417, 2023). "The degree of rescue of dedifferentiation by homozygous CDK4-R24C observed in this study was surprisingly complete, especially given the lack of improvement in insulin resistance, suggesting that loss of CDK4/cyclinD2 activity may be a primary cause of β cell failure in IRS2-null mice." (PMID 37712417, 2023). "Cyclin D2, a driver of postnatal β cell expansion and β cell compensation for insulin resistance, binds to and activates cyclin-dependent kinase (CDK) family members CDK4 and 6 to hyperphosphorylate the retinoblastoma (Rb) protein and derepress E2F transcription factors." (PMID 37712417, 2023). "Surprisingly, CDK4-R24C did not rescue insulin resistance in other metabolic tissues." (PMID 37712417, 2023).
lipomatous tumors (3 papers, 2015 to 2025). "This indicates that a combination of p16 and CDK4 is helpful in differentiating benign lipomatous tumors from atypical and dedifferentiated lipomatous tumors." (PMID 37016649, 2023). "IHC may be particularly helpful in excluding histological mimics such as angiomyolipoma (HMB-45 positive), atypical lipomatous tumors (MDM2/CDK4 positivity), or other smooth muscle tumors with ambiguous features." (PMID 40625645, 2025).
malignant pleural mesothelioma (3 papers, 2018 to 2021). A malignant neoplasm that arises from mesothelial cells in the pleura and shows a diffuse growth pattern. "Another promising combination is the potential use of locally administered microRNA-206 (which has been shown to target the RTK-Ras-MAPK-P13K/Akt-CDK pathway) and CDK4/6i, such as Abemaciclib, following successful in vitro and in vivo studies in malignant pleural mesothelioma." (PMID 34828525, 2021).
metastasis (3 papers, 2020 to 2025). The spread or migration of cancer cells from one part of the body (where they first appeared) to another. "Additional poor prognostic factors identified include high tumor grade, PR negativity, liver metastasis, and the concurrent use of CDK4/6 inhibitors with fulvestrant." (PMID 39859134, 2025). "Even considering visceral metastasis, including liver metastasis, CDK4/6 inhibition with AI was an effective treatment strategy compared with AI alone, according to previous clinical trials." (PMID 34745997, 2021).
metastatic prostate carcinoma (3 papers, 2019 to 2022). A carcinoma that arises from the prostate gland and has spread to other anatomic sites. "For example, a study discovered that cyclin-dependent kinase 4/6 (CDK4/6) phosphorylation of Rb at S249 and T252 enhances Rb interaction with p65, thereby inhibiting p65-dependent transcription of programed death-ligand 1 (PD-L1), among other genes, in metastatic prostate cancer." (PMID 33375283, 2020).
nut midline carcinoma (3 papers, 2022 to 2025). A rare, highly aggressive and lethal carcinoma that affects children and young adults. "For instance, combining CDK4/6 inhibitors or EZH2 inhibitors with BET inhibitors has demonstrated synergy, and currently, new phase I combination trials are being tested in NUT carcinoma in the USA (NCT05372640, NCT05019716, NCT05488548)." (PMID 39863772, 2025).
pituitary tumor (3 papers, 2016 to 2020). A benign or malignant neoplasm affecting the pituitary gland. "RIB-mediated perturbations in ionic currents presented herein are upstream of its suppressive action on cytosolic CDK-4/6 activities and partly participates in its modulatory effects on the functional activities of pituitary tumor cells (e.g., GH3 cells) or cardiac myocytes (e.g., HL-1 cells)." (PMID 33138174, 2020). "The first study treated CDK4/p27 double knockout mice harboring anterior pituitary tumors with flavopiridol, an inhibitor of CDK1, CDK2, CDK4, CDK6, and CDK7 that causes cell-cycle arrest at G1 and G2, and showed shrinkage of pituitary tumor size as well as prolonged survival." (PMID 30147673, 2018). "The importance of RIB-induced inhibition of CDK-4/6 activity seems to be overestimated, notwithstanding the presence of the CDK complex in the cytosol of pituitary tumor cells or heart cells." (PMID 33138174, 2020).
pleural mesothelioma (3 papers, 2020 to 2024). A neoplasm that arises from the mesothelial cells of the pleura. "In CDKN2A-mutated malignant pleural mesothelioma cell lines and in a mouse model, the inhibition of CDK4/CDK6 was shown to suppress cell viability and tumour growth." (PMID 32526924, 2020). "CDK4/6 inhibition induces a deep proliferation arrest along with senescence in most pleural mesothelioma cell lines." (PMID 36453028, 2024). "To conclude, our study supports further clinical evaluation of CDK4/6i for the treatment of pleural mesotheliomas including in various combinations with the standard therapies." (PMID 36453028, 2024).